MMP3 (matrix metallopeptidase 3)
Diseases named in the same sentence as MMP3 in open-access papers (continued):
Sharing a sentence is not in itself a finding about the gene and the disease.
cancer (continued). "The present study shows that CK2 down-regulation induces the nuclear import of NF-κB by reducing the IκB levels, which promotes the subsequent expression of SASP factors, such as IL-6, IL-1β, and MMP3 in human cancer cells." (PMID 33401686, 2021). "MMP-10 prevails over MMP-3 also in cancer tissues, but the MMP-10 content was similar in high-grade and low-grade tumors." (PMID 34441979, 2021). "It has been shown by Taha’s group that the knockout of MMP3 not only impairs cancer cell’s tumorigenic potential but also reduces the stability of cancer-derived extracellular vesicles." (PMID 34283046, 2021). "Matrix metalloproteinase 3 (MMP3) is upregulated in many cancers and responsible for the induction of EMT and exerts its action by expression of an alternatively spliced form of Rac1, which causes mitochondrial ROS accumulation." (PMID 34829708, 2021). "Accumulating reports show that overexpression of certain MMPs (e.g. MMP2, MMP3 and MMP9) is associated with EMT during cancer initiation and progression." (PMID 33931048, 2021). "ICAM1, MMP1, and MMP3 are the well-known biomarkers participating in regulating cancer cell migration and invasion." (PMID 34544905, 2021). "Of the detected metalloproteinases, the only concentration of MMP3 was significantly higher in metastatic UM-exos, which is consistent with its role in mediating cancer progression." (PMID 34283046, 2021). "MMP3-mediated cleavage of other growth factors such as heparin-bound epidermal growth factor and transforming growth factor β promotes cancer cell proliferation and epithelial-mesenchymal transition (EMT)." (PMID 34072157, 2021). "Matrix metalloproteinase 1 and 3 (MMP1 and MMP3), which are in the matrix metalloproteinase family, are also overexpressed in many cancers." (PMID 33564686, 2021). "Expression levels of MMP2 and MMP14 were similar in both tissue types; MMP3 protein expression was lower in para-cancer tissues than in HCC tissues; MMP11 protein expression was higher in HCC tissues." (PMID 34376644, 2021). "The high expression levels of MMP1 and MMP3 enhance cancer cell migration and invasion, and predict poor prognosis for NPC." (PMID 34544905, 2021). "TGFB1 was reported to induce the expression of THBS1, resulting in stimulating migration of cancer cells and driving the expression of MMP3 (matrix metalloprotease 3) via integrin signaling, conducive to OSCC intrusion." (PMID 35237609, 2021). "These experiments suggested that MMP3-rich EVs released by the more aggressive cancer cells were highly transmissive into recipient cells." (PMID 32260433, 2020). "IL7R and IL7 are highly expressed in PCa and are associated cancer cell invasion and migration probably by activating the AKT/NF-κB pathway and upregulating MMP-3 and MMP-7 expression." (PMID 32704070, 2020). "EVs derived from a rapidly metastatic cancer cell line (LuM1) were enriched in MMP3 and a C-terminal half fragment of CCN2/CTGF." (PMID 32260433, 2020). "In the current study, we focused on the roles of MMP3 in EVs of cancer cell lines for evaluating its tumorigenic potential." (PMID 32429403, 2020). "We next examined the importance of vimentin and MMP3 in the functional role of miR-515-3p in cancer metastasis." (PMID 33243974, 2020). "Previous studies have proved MMP3 (matrix metalloproteinase 3) played crucial roles in invasion and metastasis in many cancers." (PMID 32411535, 2020). "As a potential mechanism of the tumorigenesis, MMP3 in EVs can penetrate to recipient cells resulting in inducing transformation (normal to cancer cells)." (PMID 32429403, 2020). "MMP3 is one of epithelial-to-mesenchymal transition (EMT) markers in cancer metastasis, and it is well-known that MMP3 makes cancer cells detached from solid mass and transferred to distant regions of body." (PMID 32429403, 2020). "Taken together, we proved that miR-515-3p suppresses cancer invasion and metastasis by directly targeting vimentin and MMP3." (PMID 33243974, 2020).
cancer (continued). "To explore the role of MMP3 on the cellular communication in cancer, we generated an MMP3-knockout cell line from a murine high metastatic cancer cell line LuM1 using the CRISPR/Cas9 genome editing system." (PMID 32429403, 2020). "FasL can be cleaved by metalloproteinases such as MMP-7, ADAM10, and MMP-3 in various cell types and under various conditions, such as osteoblast apoptosis, T-cell activation, and the acquisition of chemoresistance by cancer cells." (PMID 32053892, 2020). "A recent study reported MMP3 to be up-regulated in both stromal fibroblasts and cancer cells by oxidative stress." (PMID 32260433, 2020). "Stromelysins (MMP-3, -10 and -11) that digest an extensive range of substrates are expressed by normal epithelial as well as cancer cells." (PMID 30792527, 2019). "MMP-3 damages the extracellular matrix inhibitor, deactivates several proteinase inhibitors and increases the proliferation of cancer cells through fibrosis, neovascularization, and tenascin-C expression." (PMID 31372176, 2019). "MMP3 is a proteolytic enzyme involved in normal and pathologic conditions such as tissue remodeling, cell signaling, or cancer." (PMID 31849957, 2019). "Several zinc‐containing matrix‐degrading endopeptidases (MMP‐1, MMP‐2, MMP‐3), which are known regulators of tissue remodeling in aging and cancer, were also included in the selected list of metformin targets." (PMID 29740925, 2018). "Specific MMPs such as MMP-3, -7, and -9 promote cancer metastasis and are modulated by WNT signaling." (PMID 29390034, 2018). "Over decades, the role of MMPs in cancer metastasis has been studied, and the MMP-3/Rac1B pathway was considered a classic." (PMID 30545369, 2018). "MMP-3 plays an important role in physiological process of tissue remodelling, but its inappropriate expression can lead to progression of cancer disease and facilitate invasion and metastasis formation." (PMID 28798935, 2017). "Nevertheless, we previously showed that the semi-automatic method that we used as a substitute, produced reliable results when we analyzed the effect of inhibitors or siRNA against EGFR, MMP3 or the Rho GTPases Rac1 and Rho in cancer cells." (PMID 29237412, 2017). "Fibroblast-derived MMP3 stimulated cancer cell proliferation, and such a role of MMP3 was also demonstrated in cancer/fibroblast co-grafts." (PMID 26992208, 2016). "The positive role of CCD18Lu-derived MMP3 in cancer cell proliferation was also verified in SKOV3 and SNU840 cell-lines." (PMID 26992208, 2016). "The growth of three cancer cell-lines in co-culture with fibroblasts was retarded by MMP3 inhibitor." (PMID 26992208, 2016). "Based on our previous observations, we noted that the expression of Mmp3, Mmp10, and Mmp13 was dramatically increased from inflammation to cancer, particularly during acute inflammatory stage (~200-fold increase)." (PMID 25742789, 2015). "While MMPs, namely MMP2 and MMP9 have been well-studied in cancer biology, less is known about the role of MMP3." (PMID 26008967, 2015). "Its role in cancer biology, however, was first recognized when enforced MMP3 expression in murine mammary gland epithelium led to early tumorigenesis." (PMID 26008967, 2015). "Hypoxia inducible factor 1, alpha subunit (HIF1A) was downregulated in common in cancer cells, while stromelysin-1 (matrix metallopeptidase 3), vascular endothelial growth factor A (VEGF-A), and neuropilin-1 were upregulated in common in fibroblasts." (PMID 26171396, 2015). "We then examined the influence of EGF on MMP9 transcription as well as on the transcription of additional MMPs (MMP-1, MMP-2, MMP-3, MMP-7, MMP-10, MMP-13, MMP14, MMP15) and of CD44, a cell adhesion glycoprotein implicated in EMT and cancer metastasis." (PMID 26084289, 2015). "How MMP3 is transcriptionally regulated, particularly in cancer models, has also remained less understood." (PMID 26008967, 2015).
cancer (continued). "We identified the region of the Snail promoter activated by MMP-3 induced ROS, finding it to contain a binding site for NF-κB, a transcription factor that has also been previously implicated in EMT and in cancer development and progression." (PMID 24811539, 2014). "In particular, CD10+ PSCs have been reported to promote cancer-stromal interactions by secreting high levels of MMP3." (PMID 24354864, 2013). "Although the molecular mechanisms of PDPN expression in CAFs are not clear, and CAFs have functional heterogeneity, we found that PDPN+ CAFs play an important role in cancer cell invasion in association with the expression of CD10, MMP2, and MMP3." (PMID 24354864, 2013). "Polymorphisms in MMP1 −1607, MMP3 −1171 and MMP9 −1562 have been associated with general cancer metastasis in a large meta-analysis." (PMID 23696797, 2013). "Polymorphisms in the MMP1, MMP2, MMP3, and MMP9 genes have been examined in studies evaluating cancer metastasis and functional polymorphisms have been identified for these genes." (PMID 23696797, 2013). "Conversely, production of MMP3, a mesenchymal marker important for cancer cell invasion and migration, was found to be decreased after 20 μg/mL epimorphin treatment but strongly upregulated at 10 μg/mL." (PMID 24039787, 2013). "This was especially true for MMP-9, MMP-3 and CycD1, the concentrations of which in cancer patients were lower by 65 (P<0.000003), 40 (P<0.0007) and 34% (P<0.0001), respectively." (PMID 20216542, 2010). "Next, we investigated production of MMP-3 and alpha 3-integrin proteins by cancer cells, resulting in higher expression level of these proteins by parental cells compared with MUC5AC suppressed cells." (PMID 20492722, 2010). "The rs679620 A MMP3 p.K45E polymorphism in the matrix metalloproteinase 3 (stromelysin-I) gene has been associated previously with differences in MMP3 activity and has been linked to cancer susceptibility in some studies." (PMID 19551141, 2009). "Colocalization of MMP-1 and MMP-3 with destruction of ECM in the invasive front of cancer tissue suggests a direct role in cancer invasion." (PMID 17919326, 2007). "Some of these genes (AKT and MMP3) are key regulators of epithelial–mesenchymal transition in cancer." (PMID 17242701, 2007). "Reflecting the importance of MMPs in normal tissue homeostasis and host resistance in cancer, we also designated three other MMPs as validated antitargets (MMP3, -8, -9)." (PMID 16538215, 2006). "In the osteoblasts_Gapd2 subpopulation, pathways such as proteoglycans in cancer (Col1a1, Col1a2, Hcls1, Hif1a, Stat3, Vav1), IL-17 signaling (Mmp13, Mmp3, S100a9, Ccl7, Cebpb), and ECM–receptor interaction (Col11a2, Col1a1, Ibsp, and Tnn) were activated (p < 0.05)." (PMID 41459160, 2025). "These ribosomal proteins are essential for protein synthesis, and their interaction with MMP3 suggests a potential influence on translation regulation, which could be an adaptation to the high protein synthesis demands of rapidly dividing cancer cells." (PMID 40362252, 2025). "Also, MMP-10 concentrations were higher in group III–IV compared to group I–II, which suggests that, as with MMP-7 and MMP-3, this enzyme is produced at higher levels in advanced stages of cancer." (PMID 40565125, 2025). "SRXN1 plays a role in reducing oxidative stress by repairing peroxiredoxins, and its interaction with MMP3 may play a role in managing the oxidative environment within cancer cells." (PMID 40362252, 2025). "Elevated MMP-3 expression has been reported in hen OC models and in various human carcinomas." (PMID 40564842, 2025). "Moreover, the inhibition of CXCR4 by WZ811 resulted in decreased mRNA expression levels of MMP3, which is a protein involved in cancer-induced bone lesions." (PMID 38474372, 2024).
cancer (continued). "To identify common epigenetically regulated drivers of metastatic phenotype of both Kmt2c and Kmt2d KO cells, we integrated significantly gained H3K4me1 and H3K27ac peaks and genes significantly upregulated in RNA-seq and scRNA-seq of cancer cells, identifying Mmp3 as the only overlapping gene." (PMID 38926506, 2024). "Consequently, MMP-3 expression in cancer cells is elevated, facilitating the maintenance of ECM homeostasis." (PMID 37469162, 2024). "The differences in the proteolytic cascade and preferred substrates may explain the distinct roles of MMP3 and MMP13 in the TME: MMP13 may be more specialized for the regulation of ECM integrity, while MMP3 may have broader roles in cancer progression." (PMID 38774209, 2024). "EGCG’s inhibition of MMP3 would be helpful to prevent cancer development." (PMID 36677584, 2023). "However, compelling evidence has shown that MMP3 promotes cancer invasion and metastasis by cleaving E-cadherin and disrupting its interaction with β-catenin." (PMID 37024866, 2023). "Furthermore, we found that most MMPs, including Mmp2, Mmp3, and Mmp9, secreted by cancer cells can degrade ECM to promote cell invasion and migration, were up-regulated in hybrid cells." (PMID 37138326, 2023). "MMP-3 is considered a prognostic factor in several types of cancers." (PMID 37513440, 2023). "Interestingly, very few studies have shown that MMP3 is downregulated in metastatic lesions compared with primary tumors of different cancers." (PMID 37940644, 2023). "The expression of both MMP-3 and MMP-1 has been linked with cancer invasion and metastasis." (PMID 36765641, 2023). "There was a significant difference between MMP-3 activities in both grades of cancer tissue." (PMID 36231910, 2022). "MMP-3 is also known to promote cancer cell growth and metastasis." (PMID 35669415, 2022). "It seems, that the level of stromelysin-1 synthesis may be similar for both cell kinds; however, cancer cells limit MMP-3 secretion to the extracellular space." (PMID 36231910, 2022). "Three genes (RUNX2, ERG and MMP3) are involved in “transcriptional misregulation in cancer”." (PMID 34830910, 2021). "Both cancer cells and stromal cells were mainly positive for MMP-3 in ADC." (PMID 33905434, 2021). "Moreover, high-grade cancer had significant increase in the amount of MMP-3 in comparison to low-grade cancer (p < 0.001)." (PMID 34441979, 2021). "BIRC3 and MMP3 promote cancer cell survival and metastasis, respectively." (PMID 34172737, 2021). "In addition, the content of MMP-10 in the control tissue, low-grade cancer and high-grade cancer was higher in comparison to MMP-3." (PMID 34441979, 2021). "Nuclear MMP-3 is correlated with cancer progression in glioma." (PMID 34204372, 2021). "One of the possible reasons could be that angiogenesis secretory factors ANGPTL7 and MMP3 are able to promote vascularization by inducing angiogenesis and thereby overexpressed in several cancers." (PMID 34072157, 2021). "Our current data indicate that LuM1-oncosomes can deliver pro-tumorigenic factor MMP3 from aggressive cancer cells to recipient cells, which MMP3 may reprogram." (PMID 32260433, 2020). "Long-term F. nucleatum stimulation may increase the risk of cell carcinogenesis by altering many inflammation- and cancer-related genes and pathways, such as Mnda, Cyp1b1, Comp, Phex, Mmp3, Tnfrsf1b, Fbln5, and Nfkb2." (PMID 33042984, 2020). "Moreover, MMP3 straining was presented in carcinoma cells, NPC tissue fibroblasts-like cells and a few lymphocytes." (PMID 32922541, 2020). "Conversely, MIAPaCa-2 cells treatment resulted in significant oncologic protein expression modulation, impacting other relevant scatter factors such as FGF basic and MMP-3, confirming a strong modulation of the expression of several cancer-related genes (right)." (PMID 31277479, 2019). "Previous studies have revealed that the TME may have a direct effect on cancer stem cells via molecules such as MMP-3 and Wnt ligands." (PMID 31906017, 2019).
cancer (continued). "MMP3-induced upregulation of Rac1b in mouse mammary epithelial cells requires stiff substrata/rigid microenvironments with compliances characteristic of breast and other stroma-rich cancers." (PMID 30621237, 2019). "Also known as stromelysin-1, Mmp3 targets degradation of proteoglycans, collagens, and elastins and this Mmp family member has been described in cancer, but little is known about Mmp3 in mouse valves." (PMID 29740591, 2018). "Expression of the Rac1 isoform Rac1b by cancer cells induces MMP-3 expression." (PMID 28831065, 2017). "EMT and MMP3 have been considered as candidate targets for cancer therapy." (PMID 29212264, 2017). "MMP-3 expression switching from stromal fibroblasts to cancer epithelial cells might be explained by the mechanisms regulating the stroma’s efforts to maintain tissue integrity and homeostasis during neoplastic transformation." (PMID 28831065, 2017). "Of three candidates, MMP3 alone was identified to increase cancer proliferation." (PMID 26992208, 2016). "To examine whether SIRT1-induced AR and MMP3 promote cancer proliferation, we co-cultured B16F10 with MEF-1 treated with siRNAs targeting them." (PMID 26992208, 2016). "Given that some of MMP enzymes are known to promote the invasion of cancer cells, we examined whether MMP3 also has such the effect on B16F10 cells." (PMID 26992208, 2016). "While many studies using cultured cells or animal models have implicated MMP3 as a functional contributor to lung, breast, and pancreatic premalignancy and cancer, much less is known about how MMP3 expression in human tumors relates to disease progression and overall survival." (PMID 26807201, 2015). "Increased cancer cell invasion was reduced upon the inhibition of IL-6, MMP-3 and u-PA." (PMID 26284488, 2015). "Taken together with prior functional studies of MMP3 in experimental models of these cancers, our findings suggest that MMP3 may offer a viable target for therapy relevant to multiple cancer types that account for a large proportion of cancer mortality." (PMID 26807201, 2015). "Microenvironment stiffness as a regulator of the MMP-3-induced EMT points towards possible specific relevance of this pathway in stiffer, more collagen-rich environments such as cancer-associated fibrosis, which are more common in highly aggressive, basal subtype cancers." (PMID 24811539, 2014). "Additionally, high MMP3 levels correlate with poor chemotherapy response in various cancers, suggesting that targeting MMP3 could improve therapeutic outcomes." (PMID 40362252, 2025). "MMP13 and its activator MMP3 may be used as biomarkers for cancer progression." (PMID 38774209, 2024). "Consequently, MMP-3 is recognized as a potential prognostic factor in various cancer types." (PMID 39769318, 2024). "Further studies revealed that CypA promotes HCC cell adhesion and metastasis through up-regulating MMP-3 and MMP-9.54,104 Thus, the current studies suggest that the up-regulation of CypA and MMPs is associated with various types of cancer, and CypA appears to play a vital role in cancer metastasis." (PMID 39513594, 2024). "Moreover, plasma concentration of MMP-10 and MMP-3 in combination with CA 15-3 may improve diagnosis of this type of cancer." (PMID 33371324, 2020). "In addition, WTAP also regulates the expression of certain genes associated with cancer cell movement, such as chemokine ligand 2 (CCL2), CCL3, matrix metalloproteinase 3 (MMP3), lysyl oxidase like 1 (LOXL1), hyaluronic acid synthase 1 (HAS1) and thrombospondin 1 (THBS1)." (PMID 32943100, 2020). "However, the vesicle-associated transport and roles of MMP3 in cancer have not previously been unveiled, mechanisms that we aimed to investigate here." (PMID 32260433, 2020). "Notably, 10 over-expressed genes (Comp, Mmp3, Adipoq, Angptl7, Fgg, Hp, Mstn, Saa1, Serpina3n, and Cxcl12) are translated into secreted proteins, and therefore, can be further explored as potential cancer cachexia biomarkers." (PMID 31013615, 2019).